HIF1A (hypoxia inducible factor 1 subunit alpha)
Diseases named in the same sentence as HIF1A in open-access papers (continued):
Sharing a sentence is not in itself a finding about the gene and the disease.
bacterial sepsis (10 papers, 2007 to 2024). "Furthermore, the glycolytic process mediated by AKT/mTOR/HIF-1α was shown to be associated with training immunity in monocytes and macrophages, and the researchers found that HIF-1a-deficient mice were unable to produce a trained immune response to bacterial sepsis." (PMID 35874739, 2022). "It has been shown that mice with a myeloid cell-specific defect in HIF-1α were unable to mount a trained immune response against bacterial sepsis." (PMID 30946009, 2019). "Mice with a myeloid cell-specific defect in HIF1α were unable to mount trained immunity against bacterial sepsis." (PMID 29483608, 2018). "The results of this work extend the observations of previous studies, which demonstrated that myeloid HIF-1α plays an essential role in the host response to bacterial sepsis." (PMID 30524296, 2018). "HIF-1α stabilization by siderophore-dependent iron chelation leading to bacteremia contrasts with the protective effect of HIF-1α stabilization by a pharmacological molecule, AKB-4924, during murine UTI." (PMID 27624128, 2016). "Targeted deletion of HIF-1α in T lymphocytes in mice with bacterial sepsis leads to higher levels of proinflammatory cytokines and stronger antibacterial capacities." (PMID 26215820, 2015). "Using the Cre-lox-P-system we generated mice with a T–cell targeted deletion of the HIF-1α gene and analysed them in an in vivo model of bacterial sepsis." (PMID 17786224, 2007). "Elevated HIF-1α levels manifest in bacterial sepsis, with the immune response to diverse bacterial pathogens such as Streptococcus pyogenes, Staphylococcus aureus, and Pseudomonas aeruginosa serves as a stimulant for the augmentation of HIF-1α levels." (PMID 38539163, 2024). "Our findings were consistent with studies showing significant overexpression of HIF1A during EOS in preterm infants (<32 weeks gestation) and during bacterial sepsis in very preterm infants." (PMID 32479514, 2020).
gastritis (10 papers, 2007 to 2025). Inflammation of the stomach. "HIF-1α expression increases in parallel to the progression from H. pylori-associated gastritis to intestinal metaplasia, dysplasia, and intestinal-type GC." (PMID 35681691, 2022). "In the H. pylori associated gastritis biopsies, HIF-1α was expressed focally, with only a small percentage of weakly positive mucosal cells identified." (PMID 17179985, 2007). "Ten of the 24 intestinal metaplastic biopsies expressed HIF-1α, and the intensity of staining was increased compared with the H. pylori associated gastritis, with one-third showing moderate nuclear staining." (PMID 17179985, 2007). "HIF-1α is linked to inflammation and immune responses, contributing to conditions like gastritis." (PMID 40731804, 2025). "Previous studies have reported that WQD regulates gastric mucosal blood flow disorders via the HIF-1α signaling pathway, thereby inhibiting the progression of chronic atrophic gastritis and its precancerous lesions." (PMID 40259338, 2025). "Myeloid-derived HIF-1α plays a protective role in H. pylori-induced gastritis by enhancing innate immune responses and modulating inflammation." (PMID 40731804, 2025). "Surprisingly, an increase in systemic inflammation and aggravation in gastritis was observed in H. pylori-infected transgenic mice where HIF-1α is inactivated specifically in the myeloid cell lineage." (PMID 35681691, 2022). "Investigation of H. pylori-positive gastritis specimens demonstrated that HIF-1α expression particularly increases in areas infiltrated by macrophages." (PMID 35681691, 2022). "Positive expression levels of STAT3, p-STAT3 and HIF-1α were significantly increased in the GAC specimens compared with the gastritis specimens, respectively (81.7 vs. 15.0, 58.3 vs. 5.0 and 63.3 vs. 10.0%; P<0.05)." (PMID 24959290, 2014). "Furthermore, studies have shown that myeloid-derived HIF-1α has a protective effect on H. pylori-induced gastritis, emphasizing the complex interaction between innate immunity and inflammation in the development of gastric pathology." (PMID 40731804, 2025). "As the normal architecture and vascular supply of gastritis-associated mucosa and intestinal metaplasia is presumably maintained, HIF-1α expression in these specimens is probably not related to cellular hypoxia, but to inflammatory processes." (PMID 17179985, 2007). "The findings highlight the possible role of HIF-1α, HIF-2α, and P4H-TM in modulating the immune and tissue remodeling processes in H. pylori-related gastritis." (PMID 40731804, 2025). "The expression levels of STAT3, p-STAT3, HIF-1α and VM were higher in patients with GAC (particularly in poorly differentiated GAC) than in those with gastritis (P<0.05)." (PMID 24959290, 2014). "In the present study, it was found that HIF-1α-positive expression was significantly increased in GAC specimens, particularly in VM GAC specimens, compared with the gastritis specimens (P<0.05)." (PMID 24959290, 2014). "The expression levels of STAT3, p-STAT3, HIF-1α and VM were assessed in 60 cases of patients with GAC and 20 cases of patients with gastritis on tissue microarrays by immunohistochemical methods." (PMID 24959290, 2014). "HIF1α, CEACAM6, and NOX4 upregulation was detected in gastritis and GC tissues." (PMID 40325849, 2025). "HIF-1α increases significantly in patients with H. pylori-positive gastritis, compared with H. pylori-negative gastritis." (PMID 35681691, 2022). "Although HIF-1α is typically absent in normal gastric mucosa, its expression intensifies progressively from Hp-induced gastritis to adenocarcinoma, indicating a potential molecular mechanism through which hypoxia exacerbates Hp infection-related gastric disorders." (PMID 38970131, 2024).
HIV-1 infection (10 papers, 2017 to 2023). The type species of lentivirus and the etiologic agent of acquired immunodeficiency syndrome (AIDS). "Overall, our results posit HIF-1α and HIEVs as key players in the pathogenesis of the inflammation that is associated with HIV-1 infection." (PMID 30206166, 2018). "To gain further insight into the causes underlying the induction of HIF-1α during HIV-1 infection of CD4+ T cells, we evaluated the hypothesis that by inducing mtROS, HIV-1 triggers HIF-1α activity." (PMID 30206166, 2018). "In summary, the present study suggests that M1 polarization of macrophages is related to glycolysis promotion via the JNK/COX-2/HIF-1α signaling axis in HIV-1 infection." (PMID 37798121, 2023). "Our study mechanistically elucidates that the JNK/COX-2/HIF-1α axis is activated to strengthen glycolysis, thereby promoting M1 polarization in macrophages in HIV-1 infection, providing a new idea for resolving chronic inflammation in clinical AIDS patients." (PMID 37798121, 2023). "Immunofluorescence results showed that HIF-1α expression was enhanced after HIV-1 infection and was mainly located in the nucleus." (PMID 37798121, 2023). "To further study the molecular mechanism of immunometabolic reprogramming by HIV-1 infection, we investigated the expression of HIF-1α, a known strong inducer of glycolysis, in HIV-1–infected MDMs." (PMID 37798121, 2023). "Hypoxia-inducible factor 1α (HIF-1α) expression is increased in HIV-1 infection, and TGF-β induces HIF-1α accumulation and activity by increasing HIF-1α protein stability." (PMID 36563749, 2023). "In the present study, we found that HIF-1α was markedly up-regulated by HIV-1 infection, and inhibition of HIF-1α reduced HIV-1–induced glycolysis and M1 polarization." (PMID 37798121, 2023). "Additional work will also be needed to investigate if inhibitors of HIF-1α are cardio-protective in the setting of HIV-1 infection." (PMID 34970611, 2021). "HIV-1 infection and protein-induced HIF-1α mediated metabolic alteration have also been shown to dysregulate cellular functionality through metabolic alteration." (PMID 32453744, 2020). "Chronic immune activation and inflammation are hallmarks of HIV-1 infection and Duette reported increased HIF-1α expression in HIV-1 infected T cells via the induction of mitochondrial ROS63." (PMID 32665623, 2020). "To functionally confirm the increase in HIF-1α activity during HIV-1 infection, we analyzed the glycolytic activity of HIV-1-infected cells." (PMID 30206166, 2018). "Before performing the analysis of HIF-1α activity during HIV-1 infection, we validated the responsiveness and HIF-1α specificity of the reporter cell line." (PMID 30206166, 2018). "Induction of HIF-1α activity by HIV-1 infection depends on the production of mitochondrial ROS triggered by cytosolic viral dsDNA." (PMID 30206166, 2018). "Altogether, our results demonstrate that by inducing the production of mitochondrial ROS, HIV-1 infection enhances HIF-1α activity." (PMID 30206166, 2018). "Here we show that HIV-1 infection induces HIF-1α activity and that this transcription factor upholds HIV-1 replication." (PMID 30206166, 2018). "We observed that HIV-1 infection enhanced HIF-1α transcriptional activity, as revealed by an increase in the mean fluorescent intensity (MFI) of the GFP reporter expression." (PMID 30206166, 2018). "Second, we demonstrate that HIV-1 infection induces the HIF-1α-dependent secretion of proinflammatory HIV-1-induced EVs (HIEVs)." (PMID 30206166, 2018). "We provide a body of evidence that indicate that dsDNA is responsible for triggering the mtROS/HIF-1α/EV response to HIV-1 infection." (PMID 30206166, 2018). "Herein, we demonstrate that an additional outcome of ROS induction during HIV-1 infection is the stabilization of HIF-1α." (PMID 30206166, 2018).
HIV-1 infection (continued). "Our results demonstrate critical and previously unrecognized roles of HIV-1-derived dsDNA, mtROS and HIF-1α in the development of inflammatory EVs during the course of HIV-1 infection." (PMID 30206166, 2018). "HIV-1 infection promotes the release of extracellular vesicles that induce HIF-1α activity in bystander cells." (PMID 30206166, 2018). "Analysis of HIF-1α mRNA levels revealed that HIV-1 infection increased the expression of HIF-1α in productively infected cells compared with mock-infected cells." (PMID 30206166, 2018). "HIF-1α accumulation was consistent with the temporal induction of a gene set of hypoxia responsive genes (e.g., CA9, PFKFB4, and VEGF) in our transcriptome analysis and the idea that HIF-1α enhances HIV-1 infection by binding hypoxia-responsive elements (HRE) present at the 5′-LTR." (PMID 36298843, 2022). "Thus, by controlling viral replication and the release of EVs, HIF-1α plays a critical role in immune dysfunction and the promotion of an inflammatory response during HIV-1 infection." (PMID 30206166, 2018). "This contrasting observation suggests that the mechanisms responsible for triggering HIF-1α during HIV-1 infection may be cell type specific." (PMID 30206166, 2018). "HIF-1α expression and transcriptional activity are induced upon HIV-1 infection." (PMID 30206166, 2018). "Promotion of HIF-1α activity by HIV-1 infection is triggered by viral nucleic acids." (PMID 30206166, 2018). "The subcellular localization of HIF-1α was also altered by HIV-1 infection." (PMID 30206166, 2018). "Modulation of either mtROS production or HIF-1α activity in cART-treated HIV-1-infected individuals could represent a therapeutic strategy to counterbalance inflammation during HIV-1 infection, thus reducing the risk of developing serious non-AIDS events." (PMID 30206166, 2018). "Altogether, these results show that HIV-1 infection triggers HIF-1α activity in vitro, promoting T cell glycolytic activity, and that CD4+ T cells from HIV-1-infected patients have higher HIF-1α protein levels than those from HIV-negative healthy individuals." (PMID 30206166, 2018). "Remarkably, silencing HIF-1α expression in CD4+ T cells reverted the promotion of cell death and production of proinflammatory cytokines induced by HIV-1 infection." (PMID 28953320, 2017). "In addition, results of immunofluorescence exhibited obviously weakened fluorescence of HIF-1α after meloxicam treatment, suggesting that COX-2 regulates the enhancement of glycolysis during HIV-1 infection through the HIF-1α pathway." (PMID 37798121, 2023). "In addition, Hif-1α can also be activated in non-hypoxic conditions, such as during human immunodeficiency virus (HIV)-1 infection in CD4 T cells, in which CD4 T cells are largely depleted via cell apoptosis." (PMID 33644036, 2020). "Interestingly, treatment with RAL and AZT did not block the increase in the activity of HIF-1α induced by HIV-1 infection, while the treatment with EFV and NVP markedly inhibited the HIV-1-mediated induction of HIF-1α." (PMID 30206166, 2018). "Taking into consideration that HIF-1α plays a central role in the control of glucose metabolism and in CD4+ T cell functionality, we aimed to study whether HIF-1α activity was modulated during HIV-1 infection." (PMID 30206166, 2018). "Our results showing that HIV-1 infection enhances the transcription and activity of HIF-1α in nonhypoxic conditions raises the hypothesis that a viral component, rather than hypoxia, is responsible for triggering HIF-1α activity in CD4+ T cells." (PMID 30206166, 2018).
hyperlipidemia (10 papers, 2010 to 2024). "A study showed that partial HIF-1A deletion attenuated hypoxia-induced contractions in fasting serum insulin and liver TG levels, thereby mediating the intermittent hypoxia-induced hyperlipidemia response." (PMID 35722157, 2022). "By contrast, hyperlipidemia suppressed HIF-1α accumulation in hypoxia, as exposure to palmitate alone reduced HIF-1α to levels seen in IR cells." (PMID 30175272, 2018). "Building upon these benchmark data, we sought to explore the impact of prolonged hyperlipidemia as well as the effect colchicine-based therapy on a variety of atheroprotective (Klotho, HOXA5, NOTCH1, and OCT4) and proatherogenic (HIF1a, SOX2, BMP4, and NANOG) genes." (PMID 36362692, 2022). "The underlying mechanism may be that hyperlipidemia does not affect the up-regulation of HIF-1α, which provides a new therapeutic idea for treating hyperlipidemia." (PMID 36072870, 2022). "In HIF-1α heterozygous knockout (HIF-1α+/−) mice subjected to CIH, CIH-induced elevations of plasma TC, and adipose tissue Angptl4 were reversed, while adipose tissue HIF-1α overexpression in transgenic mice resulted in hyperlipidemia and an increase of Angptl4." (PMID 27293515, 2016).
Hypoglycemia (10 papers, 2018 to 2026). A decreased concentration of glucose in the blood. "The association between induction of HIF-1α and iNOS and the protective effect of the CH diet against hypoxia-induced hypoglycemia was demonstrated." (PMID 31612075, 2019). "Moreover, when mice with Sirt6 deficiency were treated with an Hif-1α inhibitor, the hypoglycemia phenotype was rescued, which suggests that increased activity of Hif-1α contributes to the impaired glucose metabolism in these mice." (PMID 29535637, 2018). "Thus, we tested the hypothesis that Hltf deletion from placenta caused or exacerbated neonatal hypoglycemia via Hif-1α regulation of nutrient transporters." (PMID 29975766, 2018). "We found that deletion of HIF-1α has an acute protective effect on LPS-induced hypoglycemia." (PMID 30524296, 2018). "In a rat model of lipopolysaccharide (LPS)-induced AKI, both HIF-1α and aquaporin-1 (AQP1) were significantly upregulated within 12 h, concomitant with hypoglycemia, enhanced glycolysis, and a pro-inflammatory shift (elevated IL-6/TNF-α and reduced IL-10)." (PMID 41602837, 2026). "The accumulation of HIF-1α (and HIF-regulated vasoactive mediators) in hypoglycemia was markedly increased in the setting of even modest hypoxia." (PMID 37227777, 2023). "In an LPS-induced AKI rat model, early and significant upregulation of HIF-1α protein levels occurred synchronously with characteristic AKI pathophysiological changes, including hypoglycemia, enhanced glycolytic activity, and altered inflammatory cytokine profiles." (PMID 41602837, 2026).
kidney damage (10 papers, 2017 to 2025). "Based on the presented results, allicin delays the progression of nephropathy, likely mediated by the downregulation of the OS–hypoxia–fibrosis pathway, HIF-1α and CTGF." (PMID 33203103, 2020). "This reduction in uHIF-1α concentrations during feline CKD may reflect increased HIF-1α accumulation in renal tissue as kidney damage advances." (PMID 39748872, 2024). "Our study suggests that deacetylation of HIF‐1α induced by Sirt1 activation may have a therapeutic benefit to slow kidney damage in the aging process." (PMID 30614190, 2019). "HIF-1α, the prototypical factor involved in the transcriptional responses to cellular hypoxia, was upregulated in both the glomerular and tubular compartments at nuclear levels in Sirt3-deficient mice prior to eliciting kidney damage, and was not further increased upon the induction of renal injury." (PMID 37816025, 2023). "Similarly, serum and urine HIF-1α mRNA concentrations moved in the same direction as that occurring in nephropathy humans, despite correlation tests not being conducted during this earlier research." (PMID 39748872, 2024).
limb ischemia (10 papers, 2013 to 2025). A ischemia that involves the limb. "Importantly, increases in Ang 2 have been reported in limb ischemia and activation of Ang 2 has been linked to HIF-1α induction, and prostaglandin expression." (PMID 23950950, 2013). "The intramuscular delivery of AdCA5, an adenovirus containing a constitutively active version of HIF-1α, improved perfusion and arterial remodeling in a limb ischemia model." (PMID 41150799, 2025). "Briefly, repeated transient limb ischemia rapidly induces renal HIF1α expression, leading to EPO production and release from the kidney." (PMID 34292971, 2021). "According to current knowledge, the age-dependent impairment of HIF-1α induction leads to diminished vascular responses to limb ischemia and less effective wound healing." (PMID 31941032, 2020). "In a limb ischemia model, miR-486b-5p was previously shown to target PTEN, activating the AKT/MTOR/HIF-1α pathway and increasing angiogenesis." (PMID 39120274, 2024). "One study confirmed that MenSCs had a positive effect on models of limb ischemia, by secreting some cytokines such MMP-3, MMP-10, IL-4 and hypoxia inducible factor-1 alpha (HIF-1α)." (PMID 35274000, 2022). "The results of our study showed increased plasma inflammatory cytokines and MMP-9 levels as well as upregulated muscle HIF-1α and MMP-9 expressions shortly after limb ischemia." (PMID 32104148, 2020). "Here we investigated the therapeutic potential of inhibiting HIF-1α degradation through short hairpin RNA silencing of PHD-2 in the setting of diabetic wounds and limb ischemia." (PMID 26967994, 2016). "We have shown a similar increase in the expression of “ischemic genes”, HIF-1α and GLUT-1, as well as in the lipid metabolism genes between BM-Mono derived from the ischemic limb and contralateral limb, and we also showed increased circulating GLUT-1 during limb ischemia." (PMID 39404366, 2024).